IL6 (interleukin 6)
Diseases named in the same sentence as IL6 in open-access papers (continued):
Sharing a sentence is not in itself a finding about the gene and the disease.
aneurysm (continued). "Neuroinflammation in general, and IL-6 signaling in particular, appear to play a major role in the pathobiology and pathophysiology of aneurysm formation and aneurysmal subarachnoid hemorrhage (SAH)." (PMID 33923626, 2021). "A study revealed a positive correlation between aneurysm surface area and mean IL-6 level (Spearman's rank correlation r = 0.48; p = 0.003)." (PMID 34136544, 2021). "Lymphocyte and macrophage infiltration is a histopathological hallmark of intracerebral aneurysms, and many cytokines including IL-6, adhesion molecules, immunoglobulins, and complement factors have been detected in aneurysm tissues." (PMID 33923626, 2021). "Previous research revealed an increase ininfiltrated macrophages exhibiting a robust production of cytokines, including IL-6, IL-8, TNFα, and IL-1β, and specific patterns of macrophage polarization involving in aortic inflammation and aneurysm formation." (PMID 33158139, 2020). "The T helper 2 response was reported to be relevant to the growth of aneurysms, and hyperexpression of IL-6 and IL-8 in aortic dissection was also present, indicating that immunologic pathways were critical in aortic wall damage." (PMID 31751374, 2019). "In a study using pre- to post-operative arterial blood samples for 13 days in patients with ruptured aneurysms and intact aneurysms, an increase of TNFα, IL-1β, and IL-6, was found." (PMID 29483877, 2018). "Plasma IL-6 levels were measured in the blood samples at the orifices of the aneurysms and from peripheral veins." (PMID 26176774, 2015). "They found that circulating IL-6 was elevated within the aorta in patients with aneurysms and also correlated with the aneurysm surface area." (PMID 26166953, 2015). "Patients with high plasma IL-6 levels in the first three days of aneurysm rupture are more likely to have a poor outcome in 30 days." (PMID 26176774, 2015). "It is known that IL-6 is increased in aneurysm ruptures and remains elevated when multiorgan failure is developed." (PMID 24575415, 2014). "IL-6 is abundantly expressed in AAA, and the aneurysm has been identified as a direct source of circulating IL-6." (PMID 23349755, 2013). "The present study’s findings are notable in that CL treatment led to significant reductions not only in MMP expression but also in TNF-α and IL-6 levels, supporting its dual role in modulating both immune activation and the inflammatory cascade involved in aneurysm pathophysiology." (PMID 40868841, 2025). "Finally, there was also increased expression of pro-inflammatory endothelial chemokines (e.g., Ccl2, Il6), known to potentiate inflammatory processes and to be involved in aneurysm pathophysiology." (PMID 38965173, 2024). "For the quantitative assessment of the inflammatory process within the arterial wall of aneurysms, the authors compared mRNA expression of inflammatory molecules such as IL-1β, IL-6, and iNOS, as well as CD-68-positive macrophage counts in both groups (microbiota-depleted vs. controls)." (PMID 37928732, 2023). "Besides, the IL-8 Quotient (ratio of IL-8 in CSF versus serum) and IL-6 Quotient (ratio of IL-6 in CSF to serum) both showed a potential role in the pathogenesis of aneurysm formation." (PMID 37928138, 2023). "IL-6 is believed to act as a chemoattractant for immune cells in aneurysms." (PMID 35203568, 2022). "IL-6 is produced by aneurysm, and its expression isassociated with aneurysmal surface area." (PMID 39076643, 2022). "Similarly, in WT animals, an amplified expression of proinflammatory cytokines IL-1β and IL-6 was visible within the lesions upon aneurysm development." (PMID 33467682, 2021). "In all three subjects, all diagnostic procedures were repeated after one year of anti-IL-6 treatment: PET was normalized while CTA evidenced no aneurysms or stenosis." (PMID 33061825, 2020). "The concentration of IL-6 in the CSF of patients with unruptured aneurysms was 9.7 ± 1.4 pg/ml." (PMID 27576738, 2016).
aneurysm (continued). "In addition, S100A12, another DAMP molecule recently recognized as a common ligand of RAGE and TLR4, has been associated with production of IL-6 and MMP-2 and enhancement of aneurysm formation." (PMID 26741694, 2016). "As yet, it is unclear whether the reductions in IL-6 levels during statin therapy are relevant for the atherosclerotic process or for the process of aneurysm progression." (PMID 23349755, 2013). "A significant reduction in vascular IL-6 expression and reduced protein levels of IL-8, IL-13 and GM-CSF have been observed already after two weeks of doxycycline treatment (50–300 mg/day) in patients scheduled for aneurysm surgery." (PMID 22876748, 2012). "In accordance with the observation of pleiotropic effects of IL-6 and neuroinflammation in the brain in general, it is likely that IL-6 may mediate both protective effects and healing as well as pathological and destructive signals in aneurysm pathobiology." (PMID 33923626, 2021). "Therefore, in our study, the correlation between plasma IL-6 levels and the size of the aneurysm is less likely to be significant and the plasma IL-6 levels more likely reflected the degree of inflammation than the aneurysm size." (PMID 26176774, 2015). "Murine models have established that IL-6-knockout mice exhibit TAA attenuation, suggesting a possible novel target for aneurysm prevention in humans." (PMID 38275364, 2023). "Levels of circulating IL-6 have been found elevated in patients with AAA and TAA and correlated with the size of the aneurysm in cross-sectional studies." (PMID 38275364, 2023). "Correlation analysis revealed that IL-37 was positively correlated with IL-6, TNF-α, age, aneurysm diameter, and blood pressure." (PMID 35602104, 2022). "Correlation analysis showed that IL-37 was positively correlated with IL-6, TNF-α, age, aneurysm diameter, SBP, and DBP." (PMID 35602104, 2022). "An anti-inflammatory DPP-4 (dipeptidyl peptidase-4) inhibitor (anagliptin) has been shown to reduce aneurysm growth through NF-κ-B and ERK5 signaling involving IL-6." (PMID 33923626, 2021). "Pro-inflammatory cytokines, and particularly IL-6, have been shown to represent significant drivers of CVD, aneurysms included." (PMID 34202072, 2021). "We find significant increases in EPHA4 expression concomitant with IL6, CX3CR1, and MCP1 in unruptured and ruptured aneurysms compared to superficial." (PMID 31711546, 2019). "TLR4 signaling mediates proteinase release from VSMCs, and more important, contributes to AAA formation by promoting cytokine production, specifically IL-6 and MCP-1, during aneurysm initiation and development." (PMID 26741694, 2016). "In the wall of an AAA there is up-regulation of pro-inflammatory IL-1β, IL-6, IL-10 and TNF-α, which have been shown to positively correlate with aneurysm growth." (PMID 20964810, 2010). "We did not have access to measurements of aneurysm size, and so we were not able to estimate the predicted effect of IL6 signaling on AAA progression, limiting somewhat the clinical utility of findings for IL6 treatment." (PMID 39633572, 2025). "For instance, IL‐6 and MCP‐1 have previously been shown to promote aneurysm formation by enhancing macrophage infiltration and MMP activation; thus, targeting these molecules in animal or organoid models may validate their pathogenic roles." (PMID 40770945, 2025). "However, after 7 days of healing, all humoral inflammation markers examined (TNF-α, IL6, MMP-2, MMP-9 and FGF) were markedly increased in coiled aneurysms." (PMID 37533024, 2023). "IL-6 CSF levels may also reflect other forms of injury to the brain following SAH, i.e., early brain damage and septic complications of SAH and aneurysm treatment." (PMID 33923626, 2021).
aneurysm (continued). "In summary, although the TNF-α level and macrophage number were similar in ScSnJ and ScNJ mice during aneurysm initiation, knockout of TLR4 signaling reduced IL-6 and MCP-1 levels, suppressed HMGB1 and RAGE expression and interfered with consequent accumulation of macrophages." (PMID 26741694, 2016). "We measured a significantly lower expression of the cytokine IL-6 and significantly higher expression of macrophage colony-stimulating factor (M-CSF) and peroxisome proliferator-activated receptor (PPAR)γ in aneurysms than in controls." (PMID 26539497, 2015). "Significantly higher levels of IL-6 and IL-10 were observed in patients who did not respond to IVIG and in those who developed aneurysms in CA." (PMID 41441313, 2025).
vasculitis (63 papers, 2006 to 2026). "This case highlights that tocilizumab, by targeting the IL-6 pathway pivotal to RA-associated vasculitis and systemic inflammation, can induce rapid remission of refractory PN while facilitating glucocorticoid tapering." (PMID 41766909, 2026). "IL-6 is a multifunctional cytokine synthesized by neutrophils and monocytes/macrophages, causing vasculitis injury." (PMID 39318622, 2024). "Vasculitis causes tissue injury and releases cytokines like IL-6, IL-1β, and TNFα, which in turn trigger endothelial exocytosis and so on." (PMID 35061142, 2022). "IL-6 activates T cells and the recruitment of T cells likely contributed to the widespread vasculitis associated with Nipah virus infection and disease." (PMID 23342177, 2013). "One hypothesis is that CAR T cell activation in the CNS or meninges could cause a lymphocytic uveitis or vasculitis in ocular tissues; another is that the high cytokine levels (IL-6, IFNγ, etc.)disturb the ocular microenvironment." (PMID 41568391, 2025). "The TCZ-mediated inhibition of IL-6 binding to IL-6R may have caused a large increase in the patient’s serum IL-6 levels that in turn enhanced blood coagulation or favored an immune complex-mediated vasculitis by impairing the retinal microcirculation." (PMID 34802085, 2022). "These inflammatory cells could synthesize and secrete various pro-inflammatory cytokines and chemokines, i.e., tumor necrosis factor (TNF)-α, interferon (IFN)-γ and interleukin 6 (IL-6), to activate endothelial cells causing vasculitis." (PMID 25007068, 2014). "Similar to TNF inhibitors, other biologic agents, such as rituximab and tocilizumab (IL-6 inhibitors), have been reported to induce vasculitis in some patients." (PMID 41158918, 2025). "Complications are often due to vasculitis and endothelial cell injury, with a cytokine storm involving IL-6, TNF alpha, and IL-10 contributing to multi-organ failure." (PMID 39737257, 2024). "Macrophages and T-cells within these vasculitis lesions secrete a spectrum of proinflammatory cytokines which importantly include interleukin-1 beta and interleukin-6." (PMID 36983848, 2023). "For instance, the cytokine IL‐6, which also promotes vasculitis in Kawasaki disease, is one that increases significantly after COVID‐19 infection." (PMID 37273670, 2023). "Thromboembolism in vasculitis has been documented, where interleukin (IL)-1 and IL-6 play an important role in vasculitis-related thrombosis." (PMID 37631850, 2023). "Some Th1-related cytokines are also released during this process, and include interferon-γ, IL-1β, IL-6 and IL-8, which further exacerbate vasculitis and tissue injury." (PMID 35183233, 2022). "For example, IL-6 increases markedly during CoVID-19 infection, and it is the same cytokine that mediates vasculitis in Kawasaki syndrome." (PMID 35241158, 2022). "A large number of studies have shown that in the occurrence of KD, TNF-α, IL-6, TNFR, and other cytokines exist, and these cytokines lead to vascular endothelial cell damage in KD patients, and eventually causing vasculitis." (PMID 34484292, 2021). "Like STAT3, we found that IL-6 was enhanced in the LCWE model of KD vasculitis and its expression was reduced with anakinra treatment." (PMID 33897686, 2021). "Next, to determine the role of IL-6 in LCWE-induced KD vasculitis, we examined the impact of treatment with an IL-6R antagonist antibody on disease pathogenesis." (PMID 33897686, 2021). "The use of tocilizumab in PAN has not been approved by the United States Food and Drug Administration (FDA), but the blockage of IL-6 with tocilizumab has been used effectively to treat other forms of vasculitis." (PMID 27018080, 2016). "In previous papers we have also demonstrated associations between serological markers and activity in particular systems: anti-nucleosome antibodies and renal lupus, interleukin-6 and haematological lupus, and nitrated nucleosomes and vasculitis." (PMID 25890187, 2015).
vasculitis (continued). "IL-6 and IL-8 have been proposed to be involved in the development of vasculitis induced by rickettsial infection and are secreted in large quantities from HUVECs infected with R. conorii (Malish 7)." (PMID 26394396, 2015). "In the clinical setting, serum levels of proinflammatory mediators including IL-6 and TNFα have been shown to be increased in patients with an HCV-associated MC and are found to be particularly elevated during active vasculitis." (PMID 25419735, 2014). "In a Candida albicans-derived substances (CAD) mice model, another KD vasculitis model, IL-1β, IL-6, and TNF-α are reported to be upregulated." (PMID 23606968, 2013). "In our study, the development of vasculitis was likely related to an imbalance between inflammation and immune regulation, triggered by innate immune factors such as IL-6." (PMID 23074996, 2012). "We next determined if there are expression changes in IL-6 following LCWE-induced KD vasculitis." (PMID 39063551, 2024). "As in G-CSF-induced vasculitis, inflammatory mediators (e.g. IL-6) and Th17 are known to be involved in the pathogenesis of TAK and GCA, and a similar genetic predisposition (e.g. Th17 pathway) may explain the high prevalence in East Asia." (PMID 35960391, 2022). "IL-6 inhibition has shown clinical efficacy in several randomized controlled trials, thus representing a promising therapeutic strategy for this type of vasculitis." (PMID 31428096, 2019). "IL-8, and also IL-6, may play a role in the development of vasculitis resulting from the infection of endothelial cells by mediating the production of acute phase proteins." (PMID 29736763, 2018). "C- reactive protein (CRP) is an acute phase reaction protein, produced by the liver and triggered especially by interleukin-6 (IL-6) which is often used in the clinic as an inflammatory marker in “classical” inflammatory disease such as infections, vasculitis, tumors." (PMID 29467655, 2018). "The pathogenesis of vasculitis varies by type, but typically involves recruitment and activation of T-cells and macrophages with resultant generation of a variety of inflammatory cytokines including IL-6." (PMID 28878769, 2017). "Chronic overproduction of interleukin-6 (IL-6) fosters T helper 17 (Th17) cell expansion and polyclonal hypergammaglobulinemia potentially explaining the high rate of overlapping features with autoimmune conditions such as relapsing polychondritis or vasculitis." (PMID 40791602, 2025). "Serum concentrations of BAFF, APRIL, and other cytokines, including IL-4, IL-6, IL-10, and IL-13, can be implicated in the differentiation of B-cell lineages, while significant increases in BAFF, APRIL, IL-4, and IL-6 were observed in patients with ANCA-vasculitis." (PMID 40430184, 2025). "We also showed that inhaled hydrogen gas therapy leads to a notable decrease in IL-6 expression, which is compatible with the decrease in the formation of CALs in the LCWE murine model of KD vasculitis (p < 0.001)." (PMID 39063551, 2024). "Meanwhile, inhaled hydrogen gas therapy led to a notable decrease in IL-6 expression, which is compatible with the decrease in the formation of CALs in the LCWE murine model of KD vasculitis." (PMID 39063551, 2024). "In diseases like Kawasaki disease, blood markers such as tumour necrosis factor α (TNFα), interferon-γ (IFN-γ), interleukins (e.g., IL-6), and monocyte chemoattractant protein (MCP)-1 contribute to the development of the vasculitis process." (PMID 37629654, 2023). "The markers of vasculitis, such as CRP, interleukin 6, D-dimer, and natriuretic peptide, are elevated in serum." (PMID 34682178, 2021). "Cytokine-related skin lesion, such as vasculitis, has been reported in MCD, and was found to contribute to the overproduction of IL-6." (PMID 34889256, 2021). "Considering the major role of IL-6 in the pathogenesis of GCA, the potential use of tocilizumab in the treatment of this vasculitis has been explored." (PMID 31428096, 2019).
vasculitis (continued). "Additional experiments are needed to directly demonstrate the role for IL-6, Treg and Th17 in CAWS-induced vasculitis via antibody neutralization, genetic inactivation or cell expansion/depletion." (PMID 23074996, 2012). "The 2021 ACR/Vasculitis Foundation guidelines recommend treatment of TAK with glucocorticoids, followed by conventional disease-modifying antirheumatic drugs, then tumor necrosis factor (TNF) inhibitors or interleukin-6 (IL-6) inhibitors." (PMID 40746408, 2025). "Corresponding with previous studies, average IL-6 values of 146 ng/l and 40 ng/l were measured in the vasculitis and non-vasculitis groups, respectively." (PMID 36262692, 2022). "Using the LCWE-induced mouse model of KD vasculitis, we show that despite high IL-6 and STAT3 expression, suppression of these factors does not reduce the development of the cardiovascular lesions." (PMID 33897686, 2021). "Then, we found the expression of related inflammatory cytokines IL-6 and CCL5 were significantly decreased after treatment, it may further reduce the damage of vasculitis." (PMID 33133061, 2020). "Ucn1 stimulated IL6 expression in VSMCs and ICAM1 expression in ECs via cyclooxygenase-2, and promoted microvascular permeability during inflammation, MMP9 expression, and the development of vasculitis." (PMID 25462164, 2014). "Finally, CSF IL-6 seemed to be a good biomarker to distinguish MS from NMOSD/MOGAD (median CSF IL-6 of 3.1 vs. 27.0 pg/ml for MS and NMOSD/MOGAD, respectively, p < 0.001) and from CNS vasculitis (median CSF IL-6 for vasculitis of 27.7 pg/ml, p < 0.001)." (PMID 35401550, 2022). "However, blockade of STAT3 or IL-6 did not alter acute disease in the LCWE-induced mouse model of KD vasculitis." (PMID 33897686, 2021). "Furthermore, the expression of TNF-α, but not of IL-6, induced immune cell infiltration into the vitreous as well as vasculitis, and subsequently induced the development of fibrosis and epiretinal membranes." (PMID 34520511, 2021). "Our preliminary results demonstrating inhibition of LPS-induced aortic IL-6 gene expression and systemic IL-6 production in mice by acute mast cell degranulation support the notion that the mast cell may act as a potent negative modulator of vasculitis." (PMID 28878769, 2017). "Since IL-6 is a possible candidate for induction of vasculitis in the rat, the lack of stimulatory effect of BI 1015550 on IL-6 in the human setting may indicate that, in contrast to rats, the risk for vasculitis induction by BI 1015550 in humans may be quite low." (PMID 35517783, 2022). "Use of tumor necrosis factor inhibitors (predominantly infliximab) and the interleukin-6 inhibitor tocilizumab has also been used with success for rheumatologic irAEs, but to our knowledge, they have not been used for CPI-vasculitis." (PMID 35251725, 2022). "Among the patients with MPA, those with motor neuropathy had significantly higher total Birmingham Vasculitis Activity Scores and serum levels of C-reactive protein (CRP), tissue inhibitor of metalloproteinase-1 (TIMP-1), and interleukin-6 than patients without motor neuropathy." (PMID 36362162, 2022). "Furthermore, the induction of AAV-IL-10 prevented the expression of TNF-α and IL-6, but not GM-CSF and Dectin-2 at the early phase of CAWS-induced vasculitis." (PMID 29765083, 2018).